INS (insulin)
Diseases named in the same sentence as INS in open-access papers (continued):
Sharing a sentence is not in itself a finding about the gene and the disease.
Hyperglycemia (continued). "Variability within individual patients should be low, meaning that identical doses of insulin administered to the same patient on different occasions should lead to identical and predictable effects, thus lowering the risk of hypoglycaemia or hyperglycaemia." (PMID 20618882, 2010). "One factor that contributes and aggravates the hyperkalemia condition is that the potassium influx causes the pronounced and prolonged hyperglycemia, enhanced glycolysis, and inhibited glycogenesis from decreased insulin secretion." (PMID 20300540, 2010). "Gestational diabetes, similar to hospital acquired hyperglycaemia, is a temporary disorder of glucose homeostasis, caused by failure of beta-cells to overcome insulin resistance created by the anti-insulin hormones secreted by the placenta." (PMID 20615210, 2010). "Symptoms of the disease appear when insulin-making β cell mass gets reduced by approximately 90% leading to severe insulin deficiency and hyperglycemia." (PMID 21197448, 2010). "This form of insulitis is associated to active destruction of insulin-secreting β-cells; this is the point in time where the first mice showing overt hyperglycemia are observed." (PMID 20628601, 2010). "Alterations in carbohydrate metabolism, such as hypoglycemia and hyperglycemia, as well as insulin alterations, represent one of the most frequent causes of balance disorders." (PMID 19893939, 2009). "The risk T allele was associated with impaired insulin secretion and incretin effects, trending to postprandial hyperglycemia." (PMID 19924244, 2009). "We showed that three months of administration of both agents caused similar improvements in postprandial hyperglycemia, although different postprandial patterns of insulin secretion were observed." (PMID 19402896, 2009). "Development of postmeal hyperglycaemia coincides with a loss of first-phase insulin secretion, a decrease in insulin sensitivity and an inability to adequately suppress hepatic glucose production." (PMID 19046192, 2008). "It is characterized by absolute or relative deficiencies in insulin secretion and/or insulin action associated with chronic hyperglycemia and disturbances of carbohydrate, lipid and protein metabolism." (PMID 20040954, 2008). "In vivo, as expected, STZ treatment of rats caused hyperglycaemia and insulin, adiponectin and resistin deficiencies." (PMID 18353182, 2008). "This caused transitory hyperglycemia in the rats, with basal serum glucose levels returning to normal values in the first week of their lives, after the production of insulin by β cells normalized." (PMID 18828926, 2008). "For example, hypoglycaemia, which is caused by an excess of insulin, is a limiting factor in near-to-normal control of hyperglycaemia, and is a significant cause of morbidity and mortality." (PMID 17697384, 2007). "Defects in these transcription factors have been associated with decreased insulin production and hyperglycemia." (PMID 17941991, 2007). "Scheinin and McDonald reported that α2-agonists reduce insulin release from the pancreas and, thus, cause transient hyperglycaemia." (PMID 17244354, 2007). "This 'circulatory shock' condition is associated with a reactive hyperglycemia that is probably due to insulin resistance triggered by a catecholamine release." (PMID 17134504, 2006). "In turn, inadequate insulin intake in diabetic patients leads to progressive lean mass loss and hyperglycemia appears to accentuate the nitrogen loss." (PMID 16921407, 2005). "The physiologic basis of the response to OGTT differs from that of impaired FPG, with postprandial hyperglycemia closely linked to a blunting of early-phase insulin release." (PMID 15892894, 2005). "The abnormal release of growth hormone, cortisol, and epinephrine leads to impaired insulin secretion, and causes insulin resistance and hyperglycemia due to increased glycogenolysis, gluconeogenesis, and decreased glucose disposal." (PMID 15916471, 2005).
Hyperglycemia (continued). "Collectively, impaired pancreatic insulin secretion by aberrant Wnt5a/β-catenin activation may underlie the hyperglycemia associated with PDAC." (PMID 41593307, 2026). "Furthermore, intermittent CGM can facilitate modifications to insulin dosing during episodes of severe hyperglycemia caused by steroids." (PMID 41601933, 2026). "Genetic factors influencing insulin signaling, glucose metabolism, and pancreatic β-cell function may contribute to susceptibility to gestational hyperglycemia." (PMID 41596565, 2026). "In addition, the drug has been shown to reduce fasting blood glucose by stimulating insulin secretion and lowering glucagon secretion when blood glucose is high, which is crucial for preventing complications associated with hyperglycemia." (PMID 41364787, 2025). "Glucose oxidase generates hydrogen peroxide in a glucose concentration-dependent manner, cleaving the self-immolative moiety of the insulin prodrug to release the insulin analogue, enabling insulin activity only under hyperglycaemia and reducing hypoglycaemia risk." (PMID 40836936, 2025). "In support, elevated WHR and WC are indicative of central obesity that might impair insulin sensitivity and glucose metabolism, thereby increasing the risk of hyperglycaemia through inflammatory processes and hormonal disruption." (PMID 40289329, 2025). "From a biological viewpoint, the G risk allele in rs10830963 is corresponded with reduced insulin production and increased fasting glucose levels, which may directly promote breast cancer growth through hyperglycemia." (PMID 40736027, 2025). "This loss disrupts insulin signaling pathways, causing insulin deficiency and hyperglycemia." (PMID 40244147, 2025). "The association between selenium and hyperglycemia in pregnancy may be due to its antioxidant and insulin-mimetic functions." (PMID 40241987, 2025). "Marked hyperglycemia is confirmed, with blood glucose levels as high as 1000 mg/dL found in most patients, whereas HbA1c levels is often only mildly elevated at diagnosis, suggesting an acute loss of insulin secretion." (PMID 41010821, 2025). "The observed hyperglycemia may be attributed to impaired insulin secretion caused by oxidative damage to pancreatic β-cells." (PMID 41465846, 2025). "Although the susceptibility of female fetal under the background of hyperglycemia was also observed in a previous pregnant women cohort, the present findings lack direct mechanistic measurements (e.g., placental epigenetics, fetal insulin levels)." (PMID 40655485, 2025). "Owing to the tight interaction between T2D and MASLD, therapeutic agents targeting hyperglycemia, insulin sensitivity, and other cardiometabolic risk factors might contribute to the effective management of hepatic steatosis." (PMID 40006091, 2025). "Although this study demonstrated the potential of BCS to restore pancreatic islet β-cells and improve insulin sensitivity in the liver in a model of insulin deficiency and hyperglycemia caused by STZ-induced pancreatic islet β-cell destruction, its findings remain limited." (PMID 40002361, 2025). "Neuropathy, nephropathy, foot ulcers, and sarcopenia are symptoms of persistent hyperglycemia, lipotoxicity, excess branched-chain amino acids, and deficiencies in magnesium, zinc, and vitamin D that impair insulin signaling, mitochondrial integrity, and tissue repair." (PMID 41190158, 2025). "Similarly, the ultra‐rapid insulin period was associated with numerically lower time spent in Level 1 hyperglycaemia (>10 mM) [50.7 (15.6) vs. 59.5 (19.1)%; p = 0.098] and Level 2 hyperglycaemia (>13.9) [18.7 (17.1) vs. 27.9 (19.8)%; p = 0.136]." (PMID 40815068, 2025). "Indeed, the elevated levels of glucose associated with hyperglycaemia lead to an osmotic insult, characterised by the accumulation of sorbitol and fructose while depleting the essential osmoprotectant INS." (PMID 39797325, 2025).
Hyperglycemia (continued). "Moreover, by administering the appropriate amount of insulin, patients can maintain better control over their blood glucose levels, reducing the risk of complications like hypoglycemia and hyperglycemia." (PMID 41477679, 2025). "Earlier studies showed that administration of fructose and a low dose of STZ to rats instigated partial alteration of their pancreatic beta cells, causing IR, hyperglycemia, and decreased insulin secretion, a finding that is consistent with ours in this present study." (PMID 40735405, 2025). "Indeed, it has been observed clinically that bumetanide and other loop diuretics acting on the NKCC1 cotransporter can cause hyperglycemia, due to impaired insulin secretion." (PMID 40299635, 2025). "In overdose, the resulting excessive vasodilation and myocardial depression can lead to severe hypotension, impaired cardiac output, and organ hypoperfusion Additionally, amlodipine can impair insulin secretion and cause hyperglycemia, which compounds the effects of overdose." (PMID 41321879, 2025). "This is particularly problematic in AID systems, where even minor inaccuracies may lead to inappropriate insulin dosing, increasing the risk of hypoglycemia or hyperglycemia." (PMID 40901276, 2025). "This could represent the referred patients having a rather fast emerging hyperglycaemia due to poorer life style, less adherence of medications, or loss of insulin production." (PMID 39617955, 2025). "This case report describes a 24-year-old man with a history of hereditary chronic pancreatitis resulting from a serine protease 1 (PRSS1) gene pathogenic variant, who presented with fasting hyperglycemia and elevated glycated hemoglobin requiring early insulin therapy." (PMID 40401174, 2025). "As discussed by the authors, the results may be explained by more stable glycemia and lower glucose fluctuations, lower hypoglycemia risk and duration/frequency of hyperglycemia, and less amount of insulin units for treatment." (PMID 39998445, 2025). "However, insufficient insulin action is associated with diminished muscle glucose uptake and, consequently, hyperglycemia." (PMID 40806520, 2025). "Unlike GCK-MODY, patients with HNF4A gene variants may develop severe hyperglycemia over time, and, thus, may require insulin therapy." (PMID 40149950, 2025). "Aberrant insulin signaling is the primary cause of hyperglycemia." (PMID 39937900, 2025). "Maintaining normal blood sugar and avoiding hypoglycemia or hyperglycemia is achieved by administering the treatment (insulin) after evaluating all factors (type of insulin, blood sugar level, other associated chronic or acute diseases, stress, and hormonal imbalances)." (PMID 40004164, 2025). "Prolonged hyperglycaemia has a toxic effect on pancreatic islet cells, causing a gradual decrease in their ability to secrete insulin, making glycaemic control more difficult, and making DKA more likely to occur in the event of stress factors, such as infections and poor diet." (PMID 41244780, 2025). "Pasireotide is rarely used in pregnancy and may have limited effectiveness, but when given, can cause hyperglycemia because of insulin and incretin suppression and should be monitored carefully." (PMID 41267803, 2025). "Despite the risks associated with chronic hyperglycemia, the diminished effect of acute glycemic fluctuations in these patients implies the maintenance of stress response capacity and intact insulin signaling pathways, which are essential determinants of cardiovascular resilience." (PMID 40303637, 2025). "Moreover, β cell‐specific OGT‐deficient mice displayed hyperglycemia with insulin depletion accompanied by β cell apoptosis." (PMID 39279604, 2025). "Therefore, lower testosterone levels increase the risk of hyperglycemia and diabetes mellitus Type 2 by reducing insulin secretion and impairing glucose metabolism." (PMID 40739991, 2025).
Hyperglycemia (continued). "Without accurate guidance, users may unknowingly introduce errors that compromise the accuracy of their CGM readings, leading to inappropriate insulin dosing decisions and increased risk of hypoglycemia or hyperglycemia." (PMID 40691851, 2025). "Interestingly, glycocalyx thickness was negatively associated with insulin sensitivity indices (Matsuda index) in glucose-intolerant first-degree relatives of persons with T2D, probably due to hyperglycemia." (PMID 39998445, 2025). "Simultaneously, the frequency of hyperglycemia (>180 mg/dL) decreases, resulting in more constant metabolic management, which not only decreases the glucose toxicity but also promotes weight loss and enables reducing insulin doses." (PMID 41157142, 2025). "Consequently, patients can miss frequent bolus administrations, reduce their total daily insulin exposure, and be at considerable risk of severe hyperglycemia, ketosis, and ultimately ketoacidosis." (PMID 40914967, 2025). "Type 1 diabetes (T1D) is a chronic autoimmune disease characterized by the destruction of the insulin-producing pancreatic β-cells, leading to absolute insulin deficiency and manifested by the sudden onset of severe hyperglycemia leading to lifelong dependence on exogenous insulin." (PMID 40674727, 2025). "T1D is due to an autoimmune destruction of the insulin-producing β-cells within pancreatic islets, leading to progressive insulin deficiency and finally ensuing in hyperglycaemia and other severe metabolic perturbations, with need of exogenous insulin administration for survival." (PMID 40802787, 2025). "The general pathophysiology of diabetic ketoacidosis (DKA) involves severe insulin deficiency and an increase in insulin-antagonist hormones such as glucagon, leading to hyperglycemia because of impaired glucose utilization and increased ketone body production from excess lipolysis." (PMID 40951123, 2025). "Additionally, increased adiposity impairs insulin sensitivity, leading to hyperglycemia and dyslipidemia, both of which are major risk factors for CVD." (PMID 40630902, 2025). "As a result, the body becomes deficient in insulin and experiences hyperglycemia." (PMID 40416990, 2025). "Biologically, aging is linked to progressive declines in β-cell function and insulin sensitivity, compounded by gestational hormonal shifts, which may collectively drive hyperglycemia." (PMID 41393292, 2025). "T1DM is an autoimmune-mediated metabolic disorder characterized by the absolute deficiency of insulin secretion due to pancreatic β-cell destruction, with chronic hyperglycemia leading to devastating complications including retinopathy, nephropathy, and neuropathy." (PMID 40836269, 2025). "GLP-1 improves insulin sensitivity, facilitates glucose uptake, and regulates lipid metabolism, thereby alleviating glycolipid metabolic disturbances commonly associated with hyperglycemia and hyperlipidemia in DKD." (PMID 41048444, 2025). "Hence, interfering with insulin signalling or secretion by AAPs contributes to hyperglycaemia and elevation of risk of type 2 diabetes." (PMID 41302979, 2025). "According to the Pedersen hypothesis, in GDM, the primary expectation is that maternal hyperglycemia and associated fetal hyperglycemia lead to increased pancreatic activity, insulin production, and pancreatic growth." (PMID 40807035, 2025). "T1D is an autoimmune disease characterized by the destruction of insulin-producing pancreas β cells, leading to progressive insulin deficiency and hyperglycemia, which causes complications, such as cardiovascular diseases, neuropathy, nephropathy and retinopathy 58-60." (PMID 39897564, 2025). "By improving insulin sensitivity and reducing hyperglycemia, selenium may indirectly reduce the risk of DR onset and progression." (PMID 40255593, 2025).
Hyperglycemia (continued). "Consequently, these changes affect carbohydrate metabolism and lead to increased gluconeogenesis associated with hepatic insulin resistance, which appears to be the main factor in hyperglycemia." (PMID 39962379, 2025). "The organoid was transplanted into the kidney capsule of STZ-induced diabetic mice and showed that the organoid could secrete insulin and attenuate weight loss and hyperglycemia in mice, showing similar effects to those with fresh islet transplantation." (PMID 40926989, 2025). "The patch provided stable glycemic control for approximately 8 h and effectively responded to glycemic challenges, critically avoiding the sharp hypoglycemic nadir and subsequent rebound hyperglycemia associated with conventional subcutaneous insulin injections." (PMID 41471093, 2025). "Alterations in insulin signaling, glucose transport, and gut microbiota composition are the principal mechanistic hypotheses underlying statin-induced hyperglycemia." (PMID 41440753, 2025). "This altered thermoregulation can negatively affect glycemic control, as it may lead to reduced insulin production and sensitivity, increasing the risk of hyperglycemia." (PMID 40724678, 2025). "In the present cohort, the group with isolated fasting hyperglycemia showed higher HbA1C levels, an increased need for insulin therapy, higher neonatal birth weight, and an elevated risk for LGA neonates, aligning with relevant original studies and a meta-analysis." (PMID 40569563, 2025). "The SMARCA4 gene, through the BRG1 protein, is part of the SWI/SNF chromatin-remodeling complex, which regulates gene expression and has been shown to cause pancreatic hypoplasia, glucose intolerance, hyperglycemia, and impaired insulin secretion in mice when specifically knocked out in β cells." (PMID 41306972, 2025). "However, pasireotide carries significant risk of hyperglycemia because of its inhibitory effects on insulin and incretin secretion; this was seen in our patient, who required insulin therapy." (PMID 41267803, 2025). "This condition may cause temporary hyperglycemia, as the circulating insulin may be insufficient to maintain normal glucose homeostasis." (PMID 41036090, 2025). "Lastly, patients experiencing PHNH used higher TDDI, as hypothesized by Michael Somogyi, who stated that insulin is a cause of extreme hyperglycemia and glucose instability." (PMID 40465171, 2025). "Diabetic ketoacidosis (DKA) is a clinical syndrome of hyperglycemia, ketosis, and anion gap metabolic acidosis caused by abnormal metabolism of glucose, fat, and protein due to insufficient insulin levels or an increased level of insulin antagonist hormone." (PMID 39959617, 2025). "To determine whether muscular Dnaja3 heterozygosity would deregulate systemic glucose metabolism and cause hyperglycaemia, we assessed glucose homeostasis with glucose tolerance and insulin tolerance tests, respectively." (PMID 39132696, 2024). "Insulin is considered a high-risk time critical medication, due to its narrow therapeutic index and level of harm that can occur in the event of an error: dangerously low or high glucose levels (hypoglycaemia or hyperglycaemia)." (PMID 39666732, 2024). "Therefore, these two types of insulin pumps, using the same basal and bolus insulin doses, have the same clinical efficacy in the management of hyperglycemia, control of postprandial glucose excursion, and risk of hypoglycemia." (PMID 38599884, 2024). "This may be attributed to impaired peripheral insulin action leading to hyperglycemia, which in turn causes vascular damage, glucose neurotoxicity, and an increased risk of dementia due to the accumulation of advanced glycation end products." (PMID 39220736, 2024). "Therefore, we can assume that the observed associations of body weight and fat mass accumulation with hyperglycemia and reduced GV are mediated through a decrease in insulin sensitivity." (PMID 39335526, 2024).